NTRK1 (neurotrophic receptor tyrosine kinase 1)
Diseases named in the same sentence as NTRK1 in open-access papers (continued):
Sharing a sentence is not in itself a finding about the gene and the disease.
metastatic disease (18 papers, 2010 to 2025). "The oncogenic alternative TrkAIII splice variant (GeneBank OP866787.1) is characterized by NTRK1/TrkA exons 6, 7, and 9 skipping, and it was first identified in human NBs in association with post-therapeutic relapse and advanced-stage metastatic disease." (PMID 38534441, 2024). "In agreement with the previous findings that NTRK1 expression (encodes NGF receptor TrkA) is associated with favorable prognosis, NTRK1 was downregulated in metastatic tumors, although NGF expression was elevated." (PMID 34556815, 2021). "Stress- and drug-resistance mechanisms in NBs include alternative TrkAIII splicing of the neurotrophin receptor tropomyosin-related kinase A (NTRK1/TrkA), which correlates with post-therapeutic relapse and advanced-stage metastatic disease." (PMID 38791513, 2024). "Most patients had metastatic disease (90.6%, 96.3%, resp., p = 0.23) at baseline, and NTRK1 (44.4%, 40.5%, resp., p = 0.70) and NTRK3 (53.0%, 56.8%, resp., p = 0.72) were the most common NTRK gene fusions." (PMID 35406565, 2022). "On the other hand, clonal mutations in ARNT (OVA_047), NTRK1 (OVA_048), MYH9 (OVA_047) and PPARG (OVA_047), and subclonal mutations in ITGAV (OVA_047) and PTPRT (OVA_003) were all specific to metastatic tumours." (PMID 32099096, 2020). "Among the more novel genes we uncovered in our analysis (amplified in 4 of 10 metastatic tumors analyzed) was the neurotrophin receptor NTRK1, a tyrosine kinase growth factor receptor." (PMID 25970776, 2015). "Outside of major academic institutions with expanded fusion panels that may account for the detection of NTRK1-3 gene alterations, the vast majority of NTRK mutations may go undetected in advanced or metastatic disease." (PMID 38200576, 2024). "Molecular drivers of pediatric PTC mostly comprise gene fusions involving RET, NTRK1, and NTRK3, with TRK fusions identified in about 25% of patients at a tertiary cancer center who develop distantly metastatic disease." (PMID 40599338, 2025). "NTRK fusions discovered involved TRKA (NTRK1) in 4 patients (67%), and TRKC (NTRK3) in 2 patients (33%) with 5 unique fusion partners in primary (3/6, 50%) or metastatic tumor tissue (3/6, 50%)." (PMID 37548775, 2023).
gastric cancer (17 papers, 2015 to 2026). A primary or metastatic malignant neoplasm involving the stomach. "Therefore, a mechanistic study was conducted in NCI-N87 (high expression of NTRK1-3 but mutation of NTRK3), AGS (high expression of NTRK1-3) and MKN28 (low expression of NTRK1-3) gastric cancer cell lines." (PMID 35008821, 2021).
leukemia (16 papers, 2007 to 2023). A malignant (clonal) hematologic disorder, involving hematopoietic stem cells and characterized by the presence of primitive or atypical myeloid or lymphoid cells in the bone marrow and the blood. "After performing a comprehensive and systematic review of TrkA signaling in leukemia, another study has identified 11 cell lines that have detectable levels of NTRK1 transcripts." (PMID 31551508, 2019). "The distinctive HDAC SCORE and expression were specific for FLT3 (leukemia) and NTRK1 (NB)." (PMID 34944663, 2021). "NTRK1 and FGFR3 are HDAC class I-associated genes in leukemia and NB patients and cell lines." (PMID 34944663, 2021). "Through the analysis of transcriptomic data of 701 leukemia and NB patient samples and cell lines, we revealed that the expression of RTK, such as KIT, FLT3, AXL, FGFR3, and NTRK1, is linked with HDAC class I. Although HDAC inhibitors have antitumor activity, they also have high whole-body toxicity." (PMID 34944663, 2021). "More importantly, only NTRK1 and FGFR3 were detected to be high-scoring among both leukemia and NB patients and cell lines." (PMID 34944663, 2021). "We measured the expression of genes coding RTKs: FLT3, KIT exclusively in leukemia cell lines, PDGFRa, AXL in NB, NTRK1, FGFR3, INSR, ROR2, and RET in both NB and leukemia cells by qRT-PCR, which were top-scoring RTK-coding genes among leukemia and NB cell lines." (PMID 34944663, 2021).
osteosarcoma (15 papers, 2003 to 2025). A usually aggressive malignant bone-forming mesenchymal neoplasm, predominantly affecting adolescents and young adults. "Oncogenic NTRK1/2/3 fusions—often retaining an active kinase domain—are documented but rare in osteosarcoma cohorts." (PMID 41142827, 2025). "Kinase targets found in the analysis were for osteosarcoma (KIT), Ewing’s sarcoma (ALK), undifferentiated pleomorphic sarcoma (JAK2, ABL2), alveolar rhabdomyosarcoma (NTRK1), and leiomyosarcoma (ALK)." (PMID 29541442, 2018).
fibrosarcoma (14 papers, 2020 to 2025). A malignant mesenchymal fibroblastic neoplasm affecting the soft tissue and bone. "We report the first case of LMNA::NTRK1-rearranged spindle cell neoplasm with pigmentation, multiple recurrences, and fibrosarcoma-like malignant transformation." (PMID 41409361, 2025). "To address these knowledge gaps, we present the first case of LMNA::NTRK1-rearranged spindle cell neoplasm with pigmentation, multiple local recurrences, and fibrosarcoma-like malignant transformation." (PMID 41409361, 2025). "The NTRK gene and fusion partner was TPM3::NTRK1 (fibrosarcoma), LPPR1::NTRK2 (Ewing’s sarcoma), DAB2IP::NTRK2 (primitive neuroectodermal tumor), and RAD51B::NTRK3 (PTC)." (PMID 38967220, 2024). "Of the NTRK fusion partners we identified in pediatrics, TPM3::NTRK1 (fibrosarcoma) has been documented in pediatrics by others, and DAB2IP::NTRK2 (primitive neuroectodermal tumor) has been previously documented in adults." (PMID 38967220, 2024). "In a minority of cases, NTRK3-negative infantile fibrosarcomas have been documented to exhibit NTRK1 gene rearrangements instead." (PMID 38397049, 2024). "Among them, tumors resembling lipofibromatosis or malignant peripheral nerve sheath tumors often harbor intra-chromosomal NTRK1 rearrangements, while most infantile fibrosarcomas are characterized by canonical ETV6::NTRK3 fusions." (PMID 36801905, 2023). "While ETV6- NTRK3 fusion is common in infantile fibrosarcoma, NTRK1/3 fusion in pediatric tumors is scarce and, consequently, not well known." (PMID 32957984, 2020). "Additionally, lamin A/C (LMNA)-NTRK1 fusion has been infrequently reported in congenital infantile fibrosarcoma, cellular mesoblastic nephroma, and lipofibromatosis-like neural tumors." (PMID 32957984, 2020). "Among soft tissue sarcomas, the predominant characterization of infantile fibrosarcoma and lipofibromatosis-like neural tumors revolves around ETV6-NTRK3 fusions and NTRK1 gene rearrangements." (PMID 38397049, 2024). "NTRK1-3 fusions have been described in infantile fibrosarcoma and mesoblastic nephroma (e.g. LMNA–NTRK1, EML4–NTRK3)." (PMID 33620682, 2021). "Herein, we report a unique case of LMNA::NTRK1-rearranged spindle cell neoplasm in a 23-year-old woman, characterized by previously undescribed pigmentation, multiple local recurrences, and fibrosarcoma-like malignant transformation—features that have not been documented in prior literature." (PMID 41409361, 2025). "The negativity of ETV6 and NTRK1 excludes the possibility of infantile fibrosarcoma." (PMID 40522461, 2025).
depression (13 papers, 2011 to 2025). "The TST was performed in order to investigate the role of the NTRK1 E495K mutation in depression-like behavior mediated through cholinergic signaling." (PMID 33235206, 2020). "Rs1659400 is in strong LD with several other SNPs within the NTRK1 gene, some of which have been implicated in alcohol dependence and depression." (PMID 21711518, 2011).
spindle cell neoplasm (13 papers, 2015 to 2026). A benign or malignant neoplasm characterized by the presence of neoplastic spindle cells. "Including our case, 40 patients with LMNA::NTRK1-rearranged spindle cell neoplasms have been reported." (PMID 41409361, 2025). "Studies were included if they reported clinical, pathological, or molecular data on LMNA::NTRK1-rearranged spindle cell neoplasms." (PMID 41409361, 2025). "Histopathological, immunohistochemical, and FISH analyses proved the diagnosis of NTRK rearranged spindle cell neoplasm, with an NTRK1 gene present in approximately 20% of analyzed nuclei." (PMID 40078480, 2024). "An attempt was made to divide the NTRK1 fused spindle cell tumors into those with low and high cellular neoplasms." (PMID 33803146, 2021). "Certain tumor types, such as NTRK-rearranged spindle cell neoplasm and nodular fasciitis, are known to exhibit fusions with multiple fusion partners for invariable partner genes such as NTRK1/2/3 and USP6." (PMID 32825119, 2020). "Clinicopathological features of LMNA::NTRK1 spindle cell neoplasm in the literature." (PMID 41409361, 2025). "Neurotrophic tyrosine receptor kinase (NTRK)-rearranged spindle cell neoplasms (NTRK-RSCNs) constitute a rare, heterogeneous subset of soft tissue tumors defined by oncogenic fusions involving NTRK1, NTRK2, or NTRK3 genes." (PMID 41409361, 2025). "Recently, a novel group of CD34 and S100 co-expression spindle cell tumors with distinctive stromal and perivascular hyalinization harboring recurrent gene fusions involving RET, RAF1, BRAF, and NTRK1/2 gene has been identified." (PMID 36229858, 2022). "Spindle cell tumors with an infiltrating growth pattern reminiscent of LPF, showing mild cytological atypia have been described to present recurrent NTRK fusions, especially of NTRK1." (PMID 33803146, 2021). "TPM3::NTRK1 and LMNA::NTRK1 are common driver fusion genes in NTRK-related spindle cell neoplasms, whereas CACYBP::NTRK1 has not been reported in the literature so far." (PMID 36331594, 2023).
brain tumors (11 papers, 2007 to 2025). "A more recent study reported on the beneficial effects of foretinib treatment in entrectinib-resistant NTRK1 fusion-positive tumors (including brain tumors) bearing the NTRK1-G667C mutation." (PMID 34055785, 2021). "Typically, NTRK fusion events involve the NTRK1 or NTRK3 genes, whereas NTRK2 mutations are more frequently observed in primary brain tumors." (PMID 40647390, 2025). "Collectively, these results indicate that entrectinib is an effective inhibitor of Bcan-Ntrk1-driven brain tumours." (PMID 28695888, 2017). "During this procedure, SNUH utilized NGS with a brain tumour-targeted gene panel, identifying the TPM3::NTRK1 fusion, amplification of MDM4/AKT3, and one-copy loss of PTEN/FGFR2, leading to the diagnosis of the tumour as HGG, not otherwise specified (NOS), according to the WHO2021 criteria." (PMID 39014476, 2024).
gastrointestinal stromal tumor (11 papers, 2013 to 2023). "Furthermore, NTRK1 G595R and NTRK1 G667S mutations presented in a NSCLC patient, and a gatekeeper mutation (NTRK3 F617L) presented in a patient with gastrointestinal stromal tumor after disease progression with larotrectinib treatment." (PMID 35372074, 2022).
breast tumors (10 papers, 2011 to 2023). "The results indicated that NTRK1 gene expression was altered in 6% (52 cases) of breast tumours with 31 amplifications, 3 missense mutations, 13 mRNA upregulations and 5 mRNA downregulations." (PMID 32957504, 2020).
glioneuronal tumor (9 papers, 2017 to 2023). "STRN1::NTRK2 and ARHGEF2::NTRK1 were reported in a single case of malignant glioneuronal tumor, respectively." (PMID 36531047, 2022). "An adult patient with a BCAN:NTRK1 fused glioneuronal tumor developed disease progression after eleven months of entrectinib." (PMID 33353026, 2020). "Alvarez-Breckenridge described a case of low-grade glioneuronal tumor with BCAN::NTRK1 fusion." (PMID 36531047, 2022). "More recently, a novel MC of glioneuronal tumor (called the “glioneuronal tumor, not otherwise specified, subtype A") harboring RTK (ALK, NTRK1, NTRK2, NTRK3, and MET) fusions and MAPK (RAF1) fusions have been isolated by DNA‐methylation profiling." (PMID 37349135, 2023).
multiple myeloma (9 papers, 2019 to 2026). "Still, the MATCH basket trial is looking to enroll patients with both solid and liquid malignancies, including multiple myeloma, harboring NTRK1, NTRK2, or NTRK3 gene fusions into the larotrectinib subprotocol (NCT02465060)." (PMID 35127532, 2021). "In contrast, another patient with an NTRK1 fusion, MMRF 2490, had clonal mutations in well-known myeloma tumor suppressors EGR1 and DIS3, meaning that targeting the NTRK1 fusion alone may not have been sufficient." (PMID 32471990, 2020). "The NGF receptors TrkA (encoded by NTRK1) and p75NTR (encoded by NGFR) were not strongly or consistently expressed by MM cell lines, which was consistent with a lack of effect of recombinant NGF on myeloma cell growth." (PMID 31578352, 2019).
liver cancer (8 papers, 2018 to 2024). An epithelial or non-epithelial malignant neoplasm that arises from the liver. "However, an increased TPM of NTRK1 was found in liver cancer when compared to normal liver tissue." (PMID 38635549, 2024). "The gene expression analysis revealed over-expression of NTRK1 in liver cancer, whereas, FGFR3 was found over-expressed in lung, breast, and liver cancers compared to their expression in the respective normal tissues." (PMID 38635549, 2024).
mesenchymal tumors (8 papers, 2009 to 2025). "LMNA::NTRK1 fusion is the most common genetic event driving mesenchymal tumors with a lipofibromatosis-like neural phenotype." (PMID 36801905, 2023). "To date, most of the fusions described in mesenchymal neoplasms involve NTRK1 and NTRK3 genes and include different fusion partner genes, most common being ETV6, LMNA, and TPM3." (PMID 32860002, 2021). "Herein, we evaluated for the presence of NTRK1/3 fusion in pediatric mesenchymal tumors, clinicopathologically and immunophenotypically." (PMID 32957984, 2020). "Clone A7H6R demonstrated a higher specificity and therefore could be considered in clinical practice for screening mesenchymal tumors for NTRK1 - 3-rearrangements, eventually leading to less unnecessary reflex testing." (PMID 40232379, 2025). "From this study, we can conclude that the use of clone A7H6R for the screening of tumors with an NTRK1 - 3-rearrangement in mesenchymal neoplasms can lead to less false positive stains and eventually to less negative and costly reflex testing in mesenchymal tumors." (PMID 40232379, 2025). "During our routine molecular diagnostic work up (period 2022–2024), we found a non-pathogenic PRCC::NTRK1-rearrangement in 12 patients with mesenchymal neoplasms using a custom-made ArcherTM FusionPlexTM Sarcoma Panel." (PMID 40232379, 2025). "Although panTRK immunohistochemistry is relatively sensitive for mesenchymal tumors with NTRK1/2/3 fusions, it demonstrates imperfect specificity in skin and soft tissue mesenchymal tumors, as it can be positive in other neoplasms such as those with neural or myogenic differentiation." (PMID 39264472, 2024). "Gene fusions involving the NTRK gene family (NTRK1, NTRK2, and NTRK3) are usually described in a broad spectrum of mesenchymal tumors." (PMID 37798904, 2024). "Fusions involving NTRK1, NTRK2, and NTRK3 are oncogenic drivers occurring in a spectrum of mesenchymal neoplasms ranging from benign to highly malignant tumors." (PMID 32860002, 2021). "Similar to the consistent immunoprofile of LMNA::NTRK1 driven human mesenchymal tumors, clone 1.14, although not clone 13, showed mRNA upregulation of S100 but no expression of SOX10." (PMID 36801905, 2023).
soft tissue tumors (8 papers, 2021 to 2025). "Previously, a more aggressive subset of soft tissue tumors with distinctive LPF-like morphology were found associated with NTRK1-associated genetic abnormalities." (PMID 38635549, 2024). "Neurotrophic tyrosine receptor kinase (NTRK) neoplasms are a rare subset of soft-tissue tumors characterized by gene fusions involving NTRK1, NTRK2, or NTRK3." (PMID 40078480, 2024). "The enrichment of a neural crest gene signature in the hES-MP expressing the LMNA::NTRK1 fusion correlates with the neural features displayed by the LMNA::NTRK1 fusion-positive soft tissue tumors resembling lipofibromatosis-like neural or peripheral nerve sheath tumor phenotypes." (PMID 36801905, 2023).
COVID-19 (7 papers, 2021 to 2025). A disease caused by infection with severe acute respiratory syndrome coronavirus 2. "Several kinases, such as NTRK1 (10,495th → 29th), FYN (3902nd → 46th), ABL1 (7261st → 91st), and SRC (8965th → 56th), are being studied for repurposing several kinase inhibitors for COVID-19 treatment." (PMID 36291657, 2022).
neuropathy (7 papers, 2018 to 2026). A disorder affecting the nervous system that manifests with pain, tingling, numbness, and/or muscle weakness. "Notably, pathogenic NTRK1 mutations disrupt chaperone-assisted protein folding, triggering self-sustaining ER stress loops that impair autophagic flux and mitochondrial homeostasis —processes implicated in chemotherapy-induced neuropathy and neurodegeneration." (PMID 40722704, 2025). "Despite this, we showed that the expression especially of NGF, NGFR, NTRK1, GFRA1, GFAP, and GDNF was upregulated in patients with severe neuropathy as compared to healthy subjects and diabetic patients with subclinical neuropathy." (PMID 30648113, 2018). "Despite these mechanistic insights in neurodegeneration and neuropathy, IGF2’s spatiotemporal regulation in CPSP—particularly its interplay with NTRK1 in the context of surgical proteostatic disruption—remains uncharacterized, posing a translational barrier for precision analgesia." (PMID 40722704, 2025).
soft tissue sarcoma (7 papers, 2018 to 2025). A malignant neoplasm arising from muscle tissue, adipose tissue, blood vessels, fibrous tissue, or other supportive tissues excluding the bones. "Using an in situ proximity ligation assay, a lamin A/C (LMNA)-neurotrophic tropomyosin receptor kinase 1 (NTRK1) gene fusion encoding a functional LMNA-TRKA fusion oncoprotein was detected in the tumor of a 41-year-old woman with soft tissue sarcoma metastatic to the lung." (PMID 29764494, 2018). "CDKN2A/2B homozygous deletion exclusively occurs in soft tissue sarcoma patients with NTRK1 fusions." (PMID 37567953, 2023). "Testing on 1272 soft tissue sarcoma samples identified eight cases (<1%) with NTRK1 or NTRK3 gene fusions, with one-half of these found in patients under the age of 5 years." (PMID 31738427, 2019). "Recurrent NTRK1 gene fusions have been noted in soft tissue sarcomas characterised by a prominent myopericytic/haemangiopericytic growth pattern." (PMID 31738427, 2019). "The upregulated genes in hES-MP cells expressing the LMNA::NTRK1 fusion (clone 13 and 1.14) were found to be enriched among the statistically significant pathways involved in neuronal development, neural crest stem cells, Ewing sarcomas and other soft tissue sarcomas." (PMID 36801905, 2023).
bone tumors (6 papers, 2010 to 2025). "The association of nerve growth factor with bone neoplasms is related to its high-affinity receptor TrkA, and the gene encoding TrkA, NTRK1, may undergo fusion mutations, resulting in sustained activation of downstream pathways." (PMID 40860871, 2025). "In this study, it was found that about 34% of Chinese bone tumor patients harbored actionable targeted mutations, including CDKN2A, PTEN, FGFR1/2/3, NF1, and NTRK1/2/3." (PMID 35756627, 2022). "Unfortunately, except for targeting a few gene fusions such as NTRK1/2/3, targeted therapy for bone tumors has made slow progress." (PMID 35756627, 2022).
Ewing sarcoma (6 papers, 2016 to 2024). A small round cell tumor that lacks morphologic, immunohistochemical, and electron microscopic evidence of neuroectodermal differentiation. "The other two NTRK gene fusions in pediatrics were an LPP1::NTRK2 fusion (Ewing’s sarcoma), and a RAD51B::NTRK3 (PTC); we did not identify ETV6::NTRK3, TPR::NTRK1 – NTRK gene fusions were more commonly reported among pediatrics with solid tumors." (PMID 38967220, 2024).